IL13 (interleukin 13)
Diseases named in the same sentence as IL13 in open-access papers (continued):
Sharing a sentence is not in itself a finding about the gene and the disease.
atopic asthma (28 papers, 2008 to 2026). An asthma that is characterized by symptoms that are triggered by an allergic reaction caused by inhaled allergens such as dust mite allergen, pet dander, pollen and mold. "This study aimed to determine the association between the STAT6 rs324011 gene polymorphism and atopic asthma among Yemeni children as well as to investigate the impact of the STAT6 rs324011 polymorphism on IL-13, total IgE, and eosinophils." (PMID 40375219, 2025). "Specific methylation profiles in the IL13 locus have been shown in airway epithelium associated with atopy and atopic asthma in children, as well as nasal epithelia and blood." (PMID 33971943, 2021). "In the subgroup analysis by atopic status, we found IL-13 −1112C/T polymorphism exhibited increased atopic asthma risk." (PMID 23437086, 2013). "Variants of IL-4 and IL-13 have been associated extensively with atopic asthma, serum concentrations of IgE and susceptibility to Crohn's disease." (PMID 18625055, 2008). "A hallmark feature of atopic asthma is the elevation of T helper 2 cytokines, i.e., IL-4 and IL-13." (PMID 29720689, 2018). "Our study investigated the relationships between three genotypes (CC, CT, and TT) and IgE, IL-13, and eosinophil levels in children with atopic asthma." (PMID 40375219, 2025). "It is now generally accepted that Th2 cells and Th17 cells significantly contributed to atopic asthma, hence we detected Th2-derived cytokines—IL-4, IL-5, IL-13, and Th17-derived cytokines—IL-17A in BALF." (PMID 33013383, 2020). "In these single and multiple ascending-dose Phase 1 studies, we investigated the safety, PK, and immunogenicity of BITS7201A, a bispecific antibody targeting IL-13 and IL-17, in healthy volunteers and a subject with mild atopic asthma." (PMID 30616547, 2019). "Both IL-5 and IL-13 are effector molecules essential to type 2-inflammation, especially in atopic asthma and viral respiratory tract infections." (PMID 29768624, 2018). "Among them, IL-4 and IL-13-mediated severe atopic asthma with elevated serum IgE and periostin can be treated effectively with an anti-IgE monoclonal antibody, omalizumab, or an anti-IL-13 monoclonal antibody, lebrikizumab." (PMID 25359462, 2014). "In addition, the frequency of circulation Th2 cells that produce both IL-17A and classical Th2 cytokines (IL-4, IL-5, and IL-13) is higher in patients with atopic asthma than healthy controls." (PMID 34344357, 2021). "Although the immunopathological features of atopic asthma are well characterized as an eosinophilic bronchitis in the airways, with the inflammatory process governed by Th2 cytokines, such as IL-4, IL-5 and IL-13, the immunological and cellular profiles of non-atopic asthma are not well known." (PMID 23253516, 2012). "Atopic asthma is characterized by a Th2-skewed immune response, marked by the activation of Th2 cells that release cytokines such as Interleukin 4 (IL-4), IL-5, and IL-13, which can lead to eosinophilia, mucous production, respiratory inflammation, and airway remodeling." (PMID 40004141, 2025). "In addition, these two meta-analyses did not evaluate the association between IL-13 polymorphisms and atopic asthma." (PMID 23437086, 2013). "This case report presents a 35-year-old female with atopic asthma who developed DISR following treatment with Dupilumab, a monoclonal antibody targeting interleukin-4 and interleukin-13." (PMID 42040988, 2026). "In a mouse model of atopic asthma, pharmacologic activation of PPARG reduces the canonical Th2 cytokines IL4 and IL13 and GATA3 protein in lung extracts." (PMID 24426833, 2014). "However, we could not evaluate the association between IL-13 +1923C/T polymorphism and atopic asthma because there was only one study performed in atopic asthmatic patients." (PMID 23841068, 2013). "In this study intracellular cytokine expression of IL-2, IL-4, IL-10, IL-13, IFN-γ, and TNF-α in CD4+ and CD8+ T cells in children with atopic asthma were measured by flow cytometry." (PMID 21197090, 2010).
atopic asthma (continued). "In an atopic asthma model, IRF5 reduces lung hyperresponsiveness, mucus production, and IL13." (PMID 41516283, 2025). "In line with the increase of CCR4+ T cells in patients, T cells from atopic asthma patients secreted more of IL-5 and IL-13 than T cells from non-asthmatic control subjects." (PMID 29507584, 2018).
colon carcinoma (28 papers, 2000 to 2026). "Research indicates that in mice with IL-4Ra gene deficiency, the transmission of IL-13 signals relies on IL-13Ra2, potentially leading to the development of precancerous lesions in colon cancer." (PMID 38519926, 2024). "The addition of D1 peptide to IL-13-treated cells caused a near complete inhibition of the IL-13 prometastatic effects in both colon cancer cell lines, being particularly effective in the inhibition of the invasiveness capacity." (PMID 30318506, 2018). "Thus, IL-13 can be referred to as a pro-oncogenic factor and IL-13 polymorphism (−1112C/T) has been identified as a higher risk of colon cancer occurrence." (PMID 27533463, 2016). "These macrophages show high STAT6‐related gene expression, induced by IL4 and IL13 exposure, which is a central mechanism in colon cancer development and progression." (PMID 38037545, 2023). "IL-4/IL-13 increased the proliferation of human colon cancer cells dependent on NAPDH oxidase 1, endometriotic stomal cells, mast cells, human lymphoblasts, fibroblasts, fibro/adipogenic progenitors (FAPs)." (PMID 34863091, 2021). "IL-4/IL-4R in colon cancer cell lines Liu and colleagues found IL-4 and IL-13 increased nicotinamide adenine dinucleotide phosphate oxidase 1-related proliferation in HT-29 and DLD-1 human CC cells." (PMID 33450900, 2021). "After receptor binding, IL-4 and IL-13 can mediate tumor cell proliferation, survival, and metastasis in gastric or colon cancer." (PMID 33450900, 2021). "This review summarizes the results about the role of IL-4/IL-13 and their receptors in gastric and colon cancer." (PMID 33450900, 2021). "It was reported that IL-4 and IL-13 inhibited colon cancer cell-cell adhesion by down-regulation of E-cadherin and CEA molecules." (PMID 32832545, 2020). "Subsequently, expression of genes encoding proliferation marker Ki67, anti-apoptotic proteins BCL-2 and BCL-xL, and cell cycle regulator p21CIP1/WAF1 in colon cancer cells stimulated with IL-4 or IL-13 was determined." (PMID 32512917, 2020). "IL-4 and IL-13 increased the expression of NADPH oxidase 1 in human colon cancer cell lines, which led to the production of reactive oxygen species and cellular proliferation." (PMID 29922293, 2018). "Administration of αGalCer, but not the TH2-skewing iNKT-cell ligand OCH, led to reduced inflammation, reduced colon tumor formation and decreased IL-13." (PMID 29375569, 2017). "Taken together, these data provide evidence demonstrating that IL-4 and IL-13 upregulate NOX1 in colon cancer cells though the IL-4R/STAT6 pathway, and that GATA3 plays an important role in the transcriptional regulation of NOX1." (PMID 28498822, 2017). "Correspondingly, we found that colonic cancer cells responded to IL-4 and IL-13 stimulation with upregulation of CLDN2, significantly so in case of IL-4, while ACTA2 and TJP1 tended to be rather downregulated, significantly so in case of Caco-2 stimulation with IL-4." (PMID 32512917, 2020). "These experiments suggested that ROS generated by NOX1 might affect IL-4/IL-13-dependent signal transduction events in colon cancer." (PMID 28498822, 2017). "Herein, we deployed this technology against a colon cancer cell line; however, our additional work shows that the same approach is valid for a very different A172 glioblastoma brain tumor cell line when an anti-IL13 was used as an anchoring antibody instead of C225." (PMID 36186597, 2022). "In colon cancer, they determined the scaffolding protein FAM120A to be an essential mediator of IL13/IL13RA2 signaling through FAK, PI3K and Src." (PMID 40663259, 2025). "Furthermore, both IL-4 and IL-13 may contribute to colon cancer progression." (PMID 29922293, 2018).
colon carcinoma (continued). "It is reported that both IL4 and IL13 share signalling events in human colon carcinoma cell lines (HT29 and WiDr), and that both IL13 and IL4 induce phosphorylation of IL4 STAT (STAT6)." (PMID 12402156, 2002). "To examine the relationship between exogenous IL-4 or IL-13 exposure and the expression of NOX1, we first determined whether the NOX1-expressing colon cancer cell lines under study possessed IL-4Rα, as has been reported previously." (PMID 28498822, 2017). "Consistently, previous studies also reported that IL-13Rα2 mRNA did not be detected by RT-PCR in HT29/B6 colon cancer cells and IL-13/IL-13Rα1 pathway was shown to play a central role in the regulation of intestinal epithelial architecture and function." (PMID 27533463, 2016). "Studies have shown that IL-13 mediates extracellular matrix proteins (Fibronectin and collagen I) production by fibroblasts via STAT6 pathway, and aggressive colon tumors with collagen-rich stroma present mesenchymal features and stronger capability for invasion." (PMID 27533463, 2016). "Moreover, the authors showed an inhibition of colonic cancer cell proliferation induced by IL-13 by silencing IL13Ra1, but not IL13Ra2 gene." (PMID 32512917, 2020). "When examined in resected tissues from patients with colon cancer, the authors found increased active NADPH oxidase 1 in the tumor tissue relative to the adjacent normal colon tissue, leading them to suggest that IL-4/IL-13-driven NADPH oxidase 1 expression may drive colon carcinogenesis." (PMID 29922293, 2018).
inflammatory bowel disease (28 papers, 2016 to 2025). A spectrum of small and large bowel inflammatory diseases of unknown etiology. "Both internalization of occludin and IL-13 induced claudin-2 upregulation have also been reported in human and experimental inflammatory bowel disease models." (PMID 27467505, 2016). "ToxoROP16I/III promotes the polarization of M2 cells, and enhances the synthesis of Arg-1, IL-10, transforming growth factor-β1, and IL-13, which may ameliorate the pathogenesis of inflammatory bowel disease in an in vitro experimental model." (PMID 35911679, 2022). "In inflammatory bowel diseases, IL-13 acts predominantly on transcriptional levels." (PMID 31262043, 2019). "Increased production of pro-inflammatory cytokines, including interferon gamma (IFN-γ), TNF-α, IL-1 and IL-13 further exacerbate damage to the intestinal mucosa, as occurs in inflammatory bowel disease (IBD)." (PMID 39273791, 2024). "For example, basophilia that is independent of MCs has been associated with inflammatory bowel diseases, but in the context of myocardial infarction, basophils have been associated with tissue repair by increasing IL-4 and IL-13 levels, and altering local monocyte/macrophage responses." (PMID 38780542, 2024). "In inflammatory bowel disease (IBD) patients, however, the role of IL-13 is less clear, with contrasting results reported from patient samples." (PMID 36749569, 2023). "Interestingly, a wide variety of cytokines such as IL-13, IL-10, and TGFβ1 have been demonstrated to participate in the innate and adaptive immune response to inflammatory bowel disease (IBD)." (PMID 36776842, 2023). "However, our result also showed that level of IL-13 was increased significantly after Pingkui enema treatment although IL-13 is regarded as a marker of active UC condition, and it also has been demonstrated that IL-13 might be not essential in the development of inflammatory bowel disease." (PMID 32831864, 2020).
Insulin resistance (28 papers, 2013 to 2025). Increased resistance towards insulin, that is, diminished effectiveness of insulin in reducing blood glucose levels. "Meteorin-like is a myokine associated with IL4, IL13, certain lymphocytes, decreased inflammation, and improved insulin resistance." (PMID 35126168, 2021). "These cytokines are often associated with protective effects on the development of insulin resistance, as IL-13 production promotes an AAM phenotype and IL-5 is required for eosinophil recruitment and activation." (PMID 30755607, 2019). "Further research is needed to evaluate the possible role of IL-13 in lipid metabolism and identify novel molecular targets with the aim of reducing triglyceride levels and cardiovascular risk in patients with insulin resistance." (PMID 29675435, 2018). "In some extent, this information is consistent with our findings and suggests a progressive loss of the cellular capacity to respond to IL-13 in the scenario of insulin resistance." (PMID 29675435, 2018). "IL13 was associated with both of them, suggesting a protective role against insulin resistance and B-cell dysfunction." (PMID 28258520, 2017). "However, the role of IL-13 in the pathogenesis of insulin resistance in humans is still unclear, and potential associations of this cytokine with parameters of low-grade systemic inflammation and metabolic dysfunction remain obscure." (PMID 29675435, 2018). "We also remark the urgency of performing clinical studies evaluating whether IL-13 may represent a novel risk marker of insulin resistance in human beings." (PMID 29675435, 2018). "Besides examining its association with insulin resistance-related metabolic markers, IL-13 was also studied in terms of low-grade systemic inflammation." (PMID 29675435, 2018). "Also, IL-13 has been shown to promote insulin secretion in pancreatic beta-cells, which is associated with compensatory hyperinsulinemia aimed to counteract hyperglycemia and insulin resistance." (PMID 29675435, 2018). "Current results also allow us to speculate regarding the existence of a state of IL-13 action resistance that could be associated with increased serum IL-13 levels in insulin-resistant patients, a notion that needs to be elucidated in basic and clinical research studies." (PMID 29675435, 2018). "IL‐13 neutralizes pro‐inflammatory cytokines (such as TNF‐α and IL‐6), which were associated with the development of insulin resistance in T2DM." (PMID 39355932, 2025). "IL-10 and IL-13 are known to suppress pro-inflammatory cytokine production and play a role in insulin resistance, respectively." (PMID 41221275, 2025). "This process plays a crucial role in the development of inflammation and insulin resistance, and IL-13 controls free glucose production via the inhibition of gluconeogenesis." (PMID 41007744, 2025). "IL-13 is a cytokine involved in insulin resistance and elevated serum levels of IL-13 have been associated with insulin resistance." (PMID 34822426, 2021). "Our main goal was to examine the systemic levels of IL-13 in patients with insulin resistance, while also studying the relationship of IL-13 with anthropometric, metabolic, and low-grade systemic inflammatory markers." (PMID 29675435, 2018). "In this regard, a previous study demonstrated that IL-13 serum levels are reduced in T2D patients that exhibit increased insulin resistance." (PMID 29675435, 2018). "For this reason, it is still of enormous importance to study the role of IL-13 in the pathogenesis of insulin resistance, also evaluating the possible existence of a state of IL-13 action resistance in patients with altered insulin sensitivity." (PMID 29675435, 2018). "In parallel, IL-13 has been also shown to play a role in the development of insulin resistance in human beings." (PMID 29675435, 2018).
Insulin resistance (continued). "Further research is needed to draw conclusions regarding the capacity of white adipose cells to release IL-13 into the bloodstream and the potential role of this cytokine in the development of insulin resistance in obese patients." (PMID 29675435, 2018). "Another phenomenon captured in our study is that IL-13 serum levels appear to be extraordinarily correlated with elevated blood values of glucose in the study population, and especially in subjects with insulin resistance." (PMID 29675435, 2018). "IL-13 may also participate in low-grade systemic inflammation and insulin resistance and, indeed, higher levels of IL-13 were observed in our group with diagnosed metabolic syndrome." (PMID 36596839, 2023). "In addition, IL-33 treatment of adipocytes and ATMs induces the production of IL-5, IL-6 and IL-13 which can exert protection against insulin resistance." (PMID 36994095, 2023). "In fatty liver disease models, inhibiting IL-13 might worsen insulin resistance, inflammation, and metabolic dysfunction." (PMID 37629063, 2023). "IL-13 may help mitigate the pro-inflammatory responses and the development of insulin resistance in T2DM, resulting to a return to normal glucose homeostasis." (PMID 36678531, 2022). "Increased level of IL13 has been observed in subjects with insulin resistance." (PMID 34067751, 2021). "Interestingly our results demonstrated that the protective effect of GITR engagement on insulin resistance was critically dependent on IL-13 secretion." (PMID 30755607, 2019). "While the M1 phenotype stimulates the generation of inflammatory cytokines such as TNF-α, iNOS, CCR2, and IL-12, the M2 phenotype promotes anti-inflammatory cytokines like IL-4 and IL-13, which relieve inflammatory reactions and inhibit the development of insulin resistance." (PMID 31212747, 2019). "This apparent contradiction could be attributed to the possible role of IL-13 in the insulin resistance pathogenesis that involves the liver, adipose tissue, skeletal muscle, and pancreatic beta-cells." (PMID 29675435, 2018). "Such a state of “IL-13 action resistance” may partially explain the increment of the IL-13 serum levels in several cohorts of patients with insulin resistance, including our own study population." (PMID 29675435, 2018). "Nevertheless, recent experimental evidence in mice has now found that IL-13 may also participate in low-grade systemic inflammation and insulin resistance." (PMID 29675435, 2018). "We want to speculate that such a discrepancy could be explained by the fact that protective effects of IL-13 depend on reaching a critical concentration, in which high IL-13 levels are able to counteract the elevation of blood glucose and insulin resistance." (PMID 29675435, 2018). "The study of IL-13 in the development of insulin resistance may provide novel insights regarding the role of cytokines in the pathogenesis of metabolic disease and immune hyperactivation." (PMID 29675435, 2018). "Then, it is reasonable to speculate that IL-13 plays a protective role in insulin resistance by promoting IRS-1 and AKT phosphorylation in insulin-dependent tissues via STAT3 and STAT6 activation as well as improvement of the beta-cell function." (PMID 29675435, 2018). "On the contrary, it has been also reported that morbidly obese patients with insulin resistance exhibit higher values of serum IL-13 than normal weight controls, and bariatric surgery was able to reduce IL-13 serum concentrations after 1-year of the surgical procedure." (PMID 29675435, 2018). "In this regard it is tempting to speculate that a circulating IL-13 decrease may be interfering with anti-inflammatory responses, and therefore have a role in increasing insulin resistance in the elderly women subjected to a detraining period as observed in the current study." (PMID 32863968, 2020).